HIF1A (hypoxia inducible factor 1 subunit alpha)
Diseases named in the same sentence as HIF1A in open-access papers (continued):
Sharing a sentence is not in itself a finding about the gene and the disease.
non-small cell lung carcinoma (continued). "Based on this feedback enhancement mechanism, the researchers later confirmed that this circular HIF-1α/miR-210 interaction decreases the mortality rate and promotes the radioresistant phenotype of non-small-cell lung carcinoma cell lines." (PMID 32014012, 2020). "CircPIP5K1A induces non-small cell lung cancer progression by the regulation of miR-600/HIF-1α (hypoxia-inducible factor 1-alpha), which results in the upregulation of EMT-related factors, such as SNAIL." (PMID 31947678, 2020). "Our search was focused on the potential prognostic role of hypoxia-related HIF-1α in bone metastatic non small cell lung cancer." (PMID 31903166, 2019). "For example, concomitant overexpression of PVT1 and upregulation of HIF-1a has been shown in hypoxic non-small cell lung cancer." (PMID 31249809, 2019). "For example, PVT1 facilitates HIF-1α expression through acting as ceRNA for miR-199a-5p in non-small cell lung cancer." (PMID 30894138, 2019). "HIF-2α, at least in some tumors, shows a greater oncogenic capacity than HIF-1α, and its overexpression correlates with poor patient outcome in colorectal carcinoma, melanoma, ovarian cancer, non-small cell lung cancers, and HCC." (PMID 31817100, 2019). "In non-small cell lung cancer, HIF-1α is a downstream target of the ERK signaling, and regulates the proliferation and angiogenesis." (PMID 29748591, 2018). "HIF-1α was reported to regulate the proliferation and invasion of non-small cell lung cancer cells by interacting with PI3K/AKT pathway." (PMID 29899167, 2018). "Mechanistically, our study demonstrated that HIF-1α played an important role in the anti-metastatic effect of sotetsuflavone in non-small-cell lung cancer A549 cells." (PMID 29531823, 2018). "Low dose erlotinib-cisplatin combination exhibits its anti-tumor activity by targeting angiogenesis through modulation of c-MYC/HIF-1α/VEGF pathway in non-small cell lung cancer cells with EGFR exon 19 deletions." (PMID 30619741, 2018). "Earlier research also showed that HIF-1a is involved in apoptosis and the proliferation of non-small cell lung cancers (NSCLCs)." (PMID 27456341, 2016). "We performed a study about the expression of VEGF-A and HIF-1α and their prognosis on patients treated by surgery in stage I non-small-cell lung cancer." (PMID 26316946, 2014). "A recent study reported that overexpression of miR-199a inhibited the hypoxia-induced cell proliferation in non-small cell lung cancer by suppressing HIF-1α." (PMID 24413338, 2014). "In summary, our experimental results demonstrated that HIF-1α and survivin are highly expressed in non-small cell lung cancer and lung adenocarcinoma cell line A549 cells, and that the expression of these proteins correlated with one another." (PMID 19245702, 2009). "Immunohistochemical staining was used to detect the expression of survivin and HIF-1α in the lung tissue of 120 patients with non-small cell lung cancer (NSCLC) and 40 patients with benign pulmonary disease." (PMID 19245702, 2009). "In this study, we investigated the effect of hypoxia-inducible factor-1α (HIF-1α) on the transcriptional activity of the survivin promoter in non-small cell lung cancer (NSCLC)." (PMID 19245702, 2009). "More recently, we showed that both EGF and hypoxia can induce CXCR4 expression in non-small cell lung cancer (NSCLC) cells via the VHL/HIF-1α axis and this process is regulated by both the PI3-kinase/PTEN/AKT/mTor pathway and hypoxia." (PMID 17083723, 2006). "Furthermore, according to existing research, USP38 has been shown to regulate the stability of HIF-1α protein in non-small cell lung cancer (NSCLC)." (PMID 40936898, 2025).
non-small cell lung carcinoma (continued). "Furthermore, HIF-1α has been found to promote METTL3 expression in non-small-cell lung cancer (NSCLC) under smoking-induced stimulation." (PMID 40136363, 2025). "Additionally, an in vitro study revealed that PX-478, another HIF-1α inhibitor, enhanced T cell-mediated tumor cell killing when combined with ICIs in non-small cell lung cancer models." (PMID 41383608, 2025). "The SIRT6 may promote the growth of erlotinib-resistant non-small cell lung cancer cells by activating the HIF-1α/HK2 signaling axis to promote aerobic glycolysis in tumor cells." (PMID 39876842, 2024). "•The activation of YAP/HIF-1α pathway promotes non-small cell lung cancer." (PMID 38889502, 2024). "MARK2/4 may promote the Warburg effect and cell growth of non-small cell lung cancer through AMPKα1/mTOR/HIF-1α signaling pathway." (PMID 39588377, 2024). "A previous study found that over-expression of CHCHD2 could promote the expression of HIF-1α to adapt the hypoxia microenvironment in non-small cell lung cancer." (PMID 36627705, 2023). "miR-199a can inhibit the of non-small-cell lung cancer by regulating HIF-1α." (PMID 35342417, 2022). "Therefore, miR-21 expressed in non-small cell lung cancer cells increases their radioresistance via the upregulation of HIF-1α-promoted glycolysis." (PMID 33806538, 2021). "Succinate may act also through succinate receptor SUCNR1, which stabilizes HIF-1α in non-small cell lung cancer by engaging the downstream mediators phosphatidylinositol 3-phosphate kinase (PI3K)/Akt that phosphorylate HIF-1α on serine." (PMID 34065551, 2021). "HIF-1α may regulate the expression of LAT1, which has a notable correlation with HIF-1α in non-small cell lung cancer." (PMID 33195053, 2020). "We investigated whether digoxin could suppress tumor cell growth through HIF-1α in non-small cell lung cancer cells (A549 cells) under hypoxic conditions." (PMID 23549264, 2013). "However, in non-small cell lung cancer, β-escin inhibited the stabilization of HIF1α by hypoxia." (PMID 34439084, 2021). "Interestingly, it was found that inhibition of the OLFM4/HIF-1α axis could improve hypoxia-induced invasion, epithelial-mesenchymal transition, and chemotherapy resistance of non-small-cell lung cancer." (PMID 34912753, 2021). "However, divergent observations have arisen in separate analysis of some human cancers about the prognostic significant of HIF-1α and HIF-2α; for example, HIF-1α expression has been associated to either better or worst prognosis, depending on tumor type (i.e., renal and non-small cell lung cancers)." (PMID 31817100, 2019). "A study using human non-small cell lung cancer cell lines and clinical specimens showed that higher expression of VEGF receptor-2, a vital angiogenesis-related receptor, in cancer cells was associated with the increased level of HIF-1α expression and resistance to platinum-based chemotherapy." (PMID 25937967, 2014). "In non-small cell lung cancer (NSCLC), HIF-1α-mediated suppression of the Hippo pathway leads to YAP1 activation and subsequent ferroptosis inhibition, suggesting a potential mechanism for tumor cell survival under hypoxic conditions." (PMID 40977060, 2025). "Our results are in line with previous studies describing the prognostic value of HIF-1α and GLUT1 in patients with PDAC and PDHK1 in non-small cell lung cancer." (PMID 41438682, 2025). "In non-small cell lung cancer (NSCLC), IL-36α appeared to disrupt angiogenesis via downregulation of HIF-1α, a transcription factor of VEGFA, a major inducer of angiogenesis." (PMID 40057603, 2025).
non-small cell lung carcinoma (continued). "For example, in fibrosarcoma and non-small-cell lung cancer cell lines, autophagy-mediated BMAL1 degradation facilitates EGLN2 expression to destabilize HIF1A which ultimately increases lipid peroxidation." (PMID 37845346, 2023). "On the other hand, Shi and co-workers describe that, in non-small cell lung cancer, the expression of LAT1 is correlated with HIF1-A levels." (PMID 35053143, 2022). "Studies have shown that in non-small cell lung cancer (NSCLC), CHCHD2 and HIF-1α co-localise in both the cytoplasm and the nucleus, with CHCHD2 overexpression significantly promoting that of HIF-1α." (PMID 34616772, 2021). "We next asked if Set7/9 also affected the expression of c-Myc, HIF1A, GLUT1, and glycolytic enzymes in non-small cell lung cancer cell lines (NSCLCs)." (PMID 34692483, 2021). "It was found in a non-small cell lung cancer model that lncRNA FAM201A competitively targets miR-370, thereby upregulating HIF-1α and EGFR in cancer cells and decreasing their radiosensitivity." (PMID 33806538, 2021). "Wherein, activated by HIF1α, NDUFA4L2 inhibited ROS production by the respiratory chain of mitochondria in non-small cell lung cancer cells." (PMID 31936274, 2020). "We analyze expression of HIF-1α and VEGF-A to clinicopathologic features and survival of patients operated on stage I non-small-cell lung cancer." (PMID 26316946, 2014). "NSCLC, non-small cell lung cancer; MMP, matrix metalloproteinase; VEGF, Vascular endothelial growth factor; PTB1b, protein tyrosine phosphatase-1B; HIF-1α: Hypoxia-inducible factor 1-α." (PMID 24921708, 2014). "Our previous studies have found that HPV-16 oncoproteins promoted angiogenesis via enhancing hypoxia-inducible factor-1α (HIF-1α), vascular endothelial growth factor (VEGF), and interleukin-8 (IL-8) expression in non-small cell lung cancer (NSCLC) cells." (PMID 25058399, 2014). "In various cell types, including glioma, non-small cell lung cancer (NSCLC), and esophageal cancer cells, lactylation has been shown to promote cell proliferation by regulating signaling axes such as HIF-1α and YTHDF2-BNIP3, implying a potentially similar role in MSCs." (PMID 41210257, 2025). "Notably, previous research has indicated that elevated levels of HIF-1α and HIF-2α in non-small cell lung cancer (NSCLC) are correlated with an unfavorable prognosis for patients." (PMID 39227650, 2024). "This drug delivery system demonstrated a synergistic effect with Erlotinib and sonodynamic treatment in three-dimensional tumor spheroids culture of non-small cell lung cancer cell lines through increasing the production of ROS and downregulating EGFR and HIF-1α." (PMID 37460927, 2023). "As for non-small cell lung cancer, acriflavine, which inhibits the development of HIF-1α/β dimers, panobinostat, which degrades HIF-1α and histone deacetylase 4 (HDAC4), and oroxylin A, which binds directly to the HIF-1α bHLH-PAS domain, can reduce hypoxia-induced cisplatin resistance." (PMID 37460927, 2023). "In non-small cell lung cancer, EZH2 upregulates the expression of PD-L1 through HIF-1α, so the combination of HIF-1 inhibitors and immunotherapy may have a more substantial therapeutic effect." (PMID 36387147, 2022). "Glycine decarboxylase and HIF-1α expression were verified to be negative prognostic factors in primary resected early-stage non-small cell lung cancer." (PMID 35411037, 2022). "To further explore the effects of HIF-1α and TGF-β on the tumorigenesis of non-small cell lung cancer cells in vivo, we injected A549 cells transfected with luciferase plasmid into nude mice to observe the effects of different treatments on their tumorigenesis ability." (PMID 34930376, 2021).
non-small cell lung carcinoma (continued). "Interestingly, Liu and colleagues reported that E6 and E7 oncoproteins enhance the expression of HIF-1α, as well as of ZEB-1, SNAIL-1, SLUG, and TWIST-1 in non-small cell lung cancer (NSCLC) cells, thus promoting the EMT process." (PMID 33297475, 2020). "To directly assess the unique and overlapping functions of HIF-1α and HIF-2α, we use CRISPR gene-editing to generate isogenic H1299 non-small cell lung carcinoma cells lacking HIF-1α, HIF-2α or both." (PMID 30642030, 2019). "The expression of some down-stream genes that are under the transcription control of HIF-1α (LDH-5, VEGF, GLUT1) was not increased in the presence of the rs11549465 variant in non-small cell lung cancer samples studied by immunohistochemistry." (PMID 18980686, 2008).
cervical carcinoma (178 papers, 2008 to 2026). A carcinoma arising from either the exocervical squamous epithelium or the endocervical glandular epithelium. "Upregulation of miRNAs − 21 is associated with HIF-1α overexpression in radioresistant cervical cancer." (PMID 38965615, 2024). "High levels of HIF-1α expression in individuals with cervical cancer are associated with unfavorable long-term outcomes." (PMID 39421736, 2024). "Our results reveal a statistically significant association between high expression of the HIF1A gene and shorter overall survival in cervical cancer patients." (PMID 38425341, 2024). "Evidence indicates that a high expression of HIF1A is associated with a worse 5-year overall survival rate in cervical cancer, which is consistent with the findings of the current study." (PMID 36028854, 2022). "TRAF6, a component of non-canonical TGF-β signaling, shows several functional associations with HIF-1α, as demonstrated in colon cancer and cervical cancer cells." (PMID 35625561, 2022). "For example, a CpG dinucleotide on the HIF-1a transcription factor motifs in the promoter element of CXCL13 in cervical cancer cells was consistently methylated and thus associated with HIF-1a." (PMID 34833360, 2021). "In an animal model of cervical cancer, the tumor growth inhibition by formononetin and cisplatin has been associated with decrease in HIF-1α and VEGF expression." (PMID 32252351, 2020). "Another study in cervical cancer showed that HIF-1α upregulation was associated with low Amplitude in the Brix model (ABrix)." (PMID 31437208, 2019). "High tumoral HIF-1α expression is reported to be associated with reduced survival in oral, oropharyngeal and cervical cancers." (PMID 24165149, 2013). "Importantly, low levels of HIF1α, VEGF-A and CAIX are associated with increased survival of cervical carcinoma patient vs patients exhibiting high levels of HIF1α, VEGF-A and CAIX (n = 304)." (PMID 39695102, 2024). "In this study, we investigated whether cancer cell viability was regulated by NPHP3 expression-associated primary cilium formation via ROS-induced HIF-1α under SD conditions in HeLa human cervical cancer cells." (PMID 36498831, 2022). "Therefore, HIF-1α is highly associated with progressivity, response to radiation, as well as the prognosis of cervical cancer." (PMID 31350968, 2019). "HIF-1α is also associated with lymph node metastasis and stage of cervical cancer." (PMID 31350968, 2019). "Considering our finding and together with previous studies, stabilization and expression of HIF-1α through high-risk HPV infection is speculated to play an important role in cervical cancer progression." (PMID 23927384, 2013). "An additional effect of the presence and accumulation of HIF-1a in tumors is presumed to be the contribution to tumor chemoresistance by obstructing drug transport and uptake, whereas its overexpression is linked to worse prognosis for patients with cervical cancer." (PMID 38257813, 2024). "Researchers have identified a novel PD-L1/miR-143/HIF-1α pathway by which E6 facilitates immune suppression in cervical cancer." (PMID 40565044, 2025). "Hypoxia-related circRNAs have been demonstrated to be crucial in regulating the progress of cervical cancer by modulating HIF-1α expression under hypoxic conditions." (PMID 40004471, 2025). "When E6 was knocked out in cervical cancer cell lines, researchers observed decreased PD-L1 and HIF-1α expression and restored levels of miR-143, strongly suggesting that E6 is central to cervical cancer’s immune escape phenotype." (PMID 40565044, 2025).